MMP7 (matrix metallopeptidase 7)
Diseases named in the same sentence as MMP7 in open-access papers (continued):
Sharing a sentence is not in itself a finding about the gene and the disease.
tongue cancer (2 papers, 2020 to 2021). A malignant neoplasm affecting the tongue. "First, we measured the expression of endogenous MMP7 in two tongue cancer cell lines: SCC9 and CAL27 and found it to be relatively highly expressed in CAL27 while lower in SCC9 cells." (PMID 31937294, 2020). "To explore the effects of MMP7 in vivo, we constructed an orthotopic nude mouse tongue cancer model with silenced MMP7 in a CAL27-derived high-metastasis tongue cancer cell line LN4." (PMID 31937294, 2020). "Functional assays in vitro and in an orthotopic nude mouse transplanted tumour model in vivo revealed that MMP7 can promote tongue cancer cell proliferation, migration, and invasion." (PMID 31937294, 2020). "The effect of MMP7 on the proliferation, apoptosis, migration, invasion of tongue cancer cells was tested in appropriate ways after MMP7 siRNA knockdown or overexpression." (PMID 31937294, 2020). "Herein, all the data in our study, despite the limitations, demonstrate that MMP7 plays an oncogenic role in the tumourigenesis and metastasis of tongue cancer by promoting malignant cell proliferation, migration and invasion." (PMID 31937294, 2020). "All the functional studies intensively indicated that MMP7 could promote the tongue cancer cell motility in vitro and confirmed its oncogenic role in the tumourigenesis and progression of tongue cancer." (PMID 31937294, 2020). "Subsequently, to investigate whether MMP7 functions similarly in vivo, an orthotopic nude mouse model of tongue cancer in which MMP7 is silenced stably in LN4 was constructed." (PMID 31937294, 2020). "Nevertheless, these results clearly illustrated that MMP7 functions as a oncogene in tongue cancer and could be exploited as a meaningful therapeutic target of TSCC." (PMID 31937294, 2020). "MMP7 plays an oncogenic role in carcinogenesis and metastasis of tongue cancer, and may serve as a potential therapeutic target for tongue cancer." (PMID 31937294, 2020). "Additionally, besides proteolysis against ECM and basement membranes, how MMP7 plays its oncogene role in tongue cancer remains elusive." (PMID 31937294, 2020). "We found that MMP7 could accelerate tongue cancer cell migration and invasion in vitro." (PMID 31937294, 2020). "Therefore, MMP7 may be regarded as a prospective therapeutic target to cure tongue cancer patients." (PMID 31937294, 2020). "Because MMP7 was upregulated in TSCC and had clinical relevance, we explored whether MMP7 could accelerate the malignant behavior of tongue cancer cells in vitro." (PMID 31937294, 2020).
tongue squamous cell carcinoma (2 papers, 2020 to 2021). A squamous cell carcinoma that arises from the tongue. "The aim of our present study was to investigate the expression level of MMP7 and its functional impact on human tongue squamous cell carcinoma." (PMID 31937294, 2020). "Regrettably, the mechanism underlying how MMP7 promotes the proliferation, metastasis and invasion of tongue squamous cell carcinoma was not revealed, although we demonstrated that MMP7 acts as oncogene in TSCC, a finding that will push us to research further." (PMID 31937294, 2020). "Thus, MMP7 expression was exceedingly higher in tongue squamous cell carcinoma both at the mRNA and protein levels than in the respective nontumour tissues, suggesting that MMP7 might play an oncogenic role and a guide to warrant further investigation." (PMID 31937294, 2020). "The expression of MMP7 in human tongue squamous cell carcinoma (TSCC) specimens compared with their respective paired nontumour tissues by real-time PCR and immunohistochemical staining." (PMID 31937294, 2020).
trachoma (2 papers, 2016 to 2017). "MMP7, CXCL5 and IL-17A were strongly associated with inflammatory episodes but not with progressive scarring in two large cohorts of individuals with trachoma." (PMID 27249027, 2016). "IL-17A, CXCL5, PDGF, MMP7 and MMP9 have previously been associated with various stages of trachoma (trachomatous inflammation–follicular, TS and TT) at mRNA and protein expression levels, however they were not demonstrably up-regulated in TT cases in the present study." (PMID 27249027, 2016).
tuberculosis (2 papers, 2014 to 2019). A chronic, recurrent infection caused by the bacterium Mycobacterium tuberculosis. "Our findings show that M. tuberculosis stimulation of PBMCs differentially increased the transcript levels for MMP-1, MMP-7, MMP-10, and TIMP-1 genes in paradoxical TB-IRIS participants in 24 h cultures (pcorr ≤ 0.05) compared with non-IRIS controls." (PMID 24136296, 2014). "MMP-1, MMP-3, MMP-7, and MMP-10 gene expression was analyzed by quantitative RT-PCR in M. tuberculosis stimulated PBMCs from 16 TB-IRIS participants treated with prednisone therapy compared with 12 patients who were placebo treated over 4 weeks of prednisone versus placebo treatment." (PMID 24136296, 2014). "Upon stimulation with M. tuberculosis for 6 h, several of the MMP transcripts including MMP-1, MMP-3, MMP-7, and MMP-10 (pcorr ≤ 0.05) increased in abundance in both TB-IRIS and non-IRIS patients when compared with those of unstimulated cultures." (PMID 24136296, 2014). "However, after 24 h of stimulation with M. tuberculosis, MMP-1, MMP-7, and MMP-10 transcripts were observed to be significantly higher in the PBMC cultures of TB-IRIS as compared with those of non-IRIS patients (pcorr = 0.02, pcorr = 0.05 and p = 0.01, respectively)." (PMID 24136296, 2014).
Upper Tract Urothelial Carcinoma (2 papers, 2022 to 2023). "The highest hazard ratios were observed in upper tract urothelial carcinomas, highlighting an even stronger prognostic relevance for MMP-7 in these patients." (PMID 37175566, 2023).
alcohol dependence (1 paper, 2018). Physical and psychological dependence on alcohol. "Given mBDNF was generated from proBDNF by the cleavage enzyme such as MMP-7 and tPA35,36, future studies should elucidate whether proBDNF cleaving enzymes are altered in alcohol dependence." (PMID 29520063, 2018).
Alzheimer disease (1 paper, 2024). A progressive, neurodegenerative disease characterized by loss of function and death of nerve cells in several areas of the brain leading to loss of cognitive function such as memory and language. "These categories include WNT (WNT1, WNT3A, WNT6, AXIN2, TNF2, MMP7), Alzheimer disease presenilin (WNT1, WNT3A, WNT6, MMP7), cadherin (WNT1, WNT3A, WNT6) and Notch (LFNG, HES1) signaling pathways." (PMID 38928376, 2024).
ankylosing spondylitis (1 paper, 2015). An autoimmune chronic inflammatory disorder characterized by inflammation in the vertebral joints of the spine and sacroiliac joints. ": Serum from ankylosing spondylitis patients increases PPARD, fra-1, MMP7, OPG and RANKL expression and the OPG/RANKL ratio in MG63 cells; these effects may be due to the stimulatory effect of the serum on the Wnt pathway." (PMID 26602520, 2015).
aortic stenosis (1 paper, 2017). Aortic valve stenosis is a aortic valve disease caused by the incomplete opening of the aortic valve. "For example, MMP-2 and MMP-14 levels robustly increase in LV pressure overload models and myocardial biopsies of aortic stenosis (AS), whereas the levels of MMP-14, MMP-7, MMP-8, and MMP-9 increase in end-stage dilated cardiomyopathy." (PMID 28484397, 2017).
astrocytomas (1 paper, 2022). "Additionally, serum levels of MMP7 are higher in patients with low-grade astrocytomas compared to healthy controls and it are also higher than in patients with high grade brain tumors." (PMID 36289737, 2022).
benign breast tumour (1 paper, 2021). "Moreover, MMP-7 concentrations were enhanced in subjects with benign breast tumour in comparison to healthy controls." (PMID 33916127, 2021). "Furthermore, concentrations of all tested parameters were significantly higher in patients with stage III and IV BC in comparison to benign breast tumour subjects (p < 0.001), in whom, however, the concentration of MMP-7 was higher than in healthy participants (p = 0.03)." (PMID 33916127, 2021). "Median levels of MMP-7, MMP-26 and CA 15-3 in the total BC group were higher than in the benign breast tumour group (p = 0.013; p = 0.015; p = 0.003, respectively)." (PMID 33916127, 2021). "The concentrations of MMP-7, MMP-26 and CA 15-3 in the BC group were significantly higher than in the total control group (benign breast tumour subjects and healthy controls) (p < 0.001)." (PMID 33916127, 2021).
benign ovarian tumors (1 paper, 2012). "By cluster analysis, only MT1-MMP, MMP-7 and MMP-9 could distinguish malignant serous tumors from borderline and benign ovarian tumors." (PMID 22200690, 2012).
benign prostatic hyperplasia (1 paper, 2017). A non-cancerous nodular enlargement of the prostate gland. "We conclude that tissue levels of MMP3 and MMP7 (finely regulated by their inhibitors TIMP1 and TIMP2) are altered in PCa compared to benign prostatic hyperplasia, which is of special relevance in elderly men." (PMID 28471417, 2017).
bladder tumor (1 paper, 2017). "In total, five articles investigating four different MMPs types (MMP1, MMP7, MMP9, and MMP11) reported a relationship between abnormal levels of MMPs and bladder tumor progression." (PMID 28427222, 2017).
brain tumors (1 paper, 2022). "The MMPs that are known to be involved in paediatric-type diffuse low-grade gliomas brain tumors are mainly MMP2 and MMP7." (PMID 36289737, 2022).
breast adenocarcinoma (1 paper, 2013). "MMP7 mRNA was detected in the neoplastic epithelial tumor cells of 70-91% of breast adenocarcinomas, and the expression of MMP7 in the mammary epithelium was known to contribute to the early-stage mammary tumorigenesis." (PMID 24143235, 2013).
cerebral infarct (1 paper, 2012). "Many methalloproteinases showed highly altered expression, including MMP2 and MMP7 at 3 d after cerebral infarct, as well as MMP9 and MMP12 in the acute (24 h) phase." (PMID 23284893, 2012). "Several matrix-methaloproteinases such as MMP2, MMP7, MMP9 and MMP12, were up-regulated after cerebral infarct." (PMID 23284893, 2012).
cervical (1 paper, 2012). "No significant change in staining for MMP-7 and cytokeratin 8/18 along with the grade of cervical squamous epithelial disease was observed." (PMID 22863036, 2012).
cervical squamous cell carcinoma (1 paper, 2022). A squamous cell carcinoma arising from the cervical epithelium. "The results demonstrated that cervical squamous cell carcinoma and endocervical adenocarcinoma (CESC) had the highest alteration frequencies involving MMP7, which was found to be around 8% with “amplification” as the elementary alteration type." (PMID 35785154, 2022).
cholesteatoma (1 paper, 2012). A pathologic process characterized by the proliferation of keratinizing squamous epithelium resulting in the accumulation of keratin and cells in the middle ear and/or mastoid. "Among the 811 up-regulated extramatrix protein genes, MMP1, MMP7, MMp9, MMP10 and MMP12 and their substrate Osteopontin (SPP1) were amplified and their expression was significantly higher in cholesteatoma than in external canal skin (logFC>10)." (PMID 23285167, 2012).
congenital heart disease (1 paper, 2024). A heart disease that is present at birth. "There is a pressing need to determine the utility of MMP-7 levels in infants with congenital heart disease (CHD) to avoid unnecessary invasive diagnostic procedures in this high-risk population." (PMID 39483898, 2024).
coronary artery atherosclerosis (1 paper, 2021). "In our study, MMP-7 and MMP-12 levels were also significantly higher in patients with CHD and verified coronary artery atherosclerosis than in the control group." (PMID 34205079, 2021).
demyelination (1 paper, 2025). "Overall, we conclude that the lack of MMP7 does not markedly impair OPC differentiation following acute cuprizone‐induced demyelination, although the temporal dynamics of OPC differentiation appear to be subtly altered." (PMID 40059514, 2025). "Therefore, the absence of MMP7 does not markedly impair the microglia and astrocyte response to acute cuprizone‐induced demyelination." (PMID 40059514, 2025).
desmoid tumor (1 paper, 2013). A desmoid tumor (DT) is a benign, locally invasive soft tissue tumor associated with a high recurrence rate but with no metastatic potential. "The transcription regulation of matrilysin requires the LEF-1/TCF beta-catenin pathways and a correlation between beta-catenin widespread nuclear expression and MMP7 overexpression was reported in sporadic desmoid tumors." (PMID 24143235, 2013).
diabetic retinopathy (1 paper, 2014). "In diabetic retinopathy altered expression and activity of MMP-7 has been shown to impair the homeostatic balance between the pro-form and cleaved active form of NGF and contribute to neurovascular dysfunction." (PMID 25158309, 2014).
Fibroadenoma (1 paper, 2023). A benign tumor of the breast characterized by the presence of stromal and epithelial elements. "An identical correlation, but only for MMP-7 concentrations, was observed when evaluating concentrations in patients with fibroadenoma lesions before and after surgery (p = 0.002)." (PMID 37048701, 2023). "Additionally, significantly higher concentrations of MMP-7 (1.62 ng/mL) were observed in fibroadenoma group in comparison to healthy women group (p < 0.0001)." (PMID 37048701, 2023).
fibrosarcoma (1 paper, 2024). A malignant mesenchymal fibroblastic neoplasm affecting the soft tissue and bone. "Specifically, it inhibits MMP-1, MMP-3, MMP-7, MMP-9, and MMP-14, which hinders the expansion of HUVECs and the activated process of proMMP-2 regulated by MMP-14 in human fibrosarcoma cells." (PMID 38611849, 2024).
focal segmental glomerulosclerosis (1 paper, 2014). A renal disorder characterized by sclerotic lesions in the glomeruli. "Moreover, MMP-7, another member of the MMP family, has been considered as a noninvasive biomarker of profibrotic signaling in obstructive nephropathy and focal segmental glomerulosclerosis." (PMID 24396399, 2014).
gallbladder cancer (1 paper, 2022). "Downregulation of MMP7 leads to a reduced proliferation and migration of tumor cells in gallbladder cancer and reduces the cisplatin resistance in NCSLC cells." (PMID 36009404, 2022).
gout (1 paper, 2021). A condition characterized by painful swelling of the joints, which is caused by deposition of urate crystals. "The MMP7 variant rs17098236 has been associated with gout and HIV infection but not functionally characterized." (PMID 34467240, 2021).
hematoma (1 paper, 2020). A hematoma is a collection of blood from a vascular structure into an extravascular space. "In CHN, TIMP-1 was associated with admission-hematoma volume and MMP-7 was elevated in patients with deep when compared to lobar hematoma." (PMID 32587306, 2020). "In VdH, admission-hematoma volume was associated with TIMP-1 and MMP-7." (PMID 32587306, 2020).
Hydrocephalus (1 paper, 2021). Hydrocephalus is an active distension of the ventricular system of the brain resulting from inadequate passage of CSF from its point of production within the cerebral ventricles to its point of absorption into the systemic circulation. "Therefore, the interplay of IL-6, IL-8, IL-10, MMP-7 and MMP-9 is worth future investigations to improve our understanding of the molecular and cellular events driving hydrocephalus." (PMID 33514409, 2021).
hydronephrosis (1 paper, 2022). Collection of urine in the renal pelvis that results in dilatation of the renal pelvis and calyces. "Urinary MMP-2, MMP-7, TIMP-2, and NGAL were measured as well as clinical characteristics including hydronephrosis grade, differential renal function, t1/2, and UPJO etiology." (PMID 35834547, 2022).
Hyperglycemia (1 paper, 2019). An increased concentration of glucose in the blood. "In our conditions, hyperglycemia did not have a direct effect on proteases as only MMP-7 was affected." (PMID 31415598, 2019).
insomnia (1 paper, 2023). A sleep disorder characterized by difficulty in falling asleep and/or remaining asleep. "Higher levels of CCL23, CD4, Gal-1 and MMP7 at baseline were all strongly associated with insomnia at EOT." (PMID 37936126, 2023). "In this study, high levels of four inflammatory proteins; CCL23, CD4, Gal-1, and MMP7, at baseline correlated strongly with insomnia at EOT." (PMID 37936126, 2023).
internal carotid artery stenosis (1 paper, 2014). Carotid stenosis is a narrowing or constriction of the inner surface (lumen) of the carotid artery, usually caused by atherosclerosis. "Plasma levels of MMP-7 were measured in 182 consecutive patients with moderate (50–69%) or severe (≥70%) internal carotid artery stenosis, and in 23 healthy controls." (PMID 24400123, 2014).
intestinal cancer (1 paper, 2019). "Our data suggest that SREBP1 promotes the expression of MMP7 by activating the phosphorylation of p65 and thus the NF-κB pathway, leading to an increase in the invasive capacity of intestinal cancer cells." (PMID 31299935, 2019).
intestinal inflammation (1 paper, 2022). "The results showed that PD significantly reduces the MMP-7+ Ly6G+ neutrophils and MMP-7+ F4/80+ macrophages among MMP-7+ CD45+ infiltrating immune cells, identifying a positive correlation between MMP-7 expression and leukocyte infiltration in DSS-induced intestinal inflammation." (PMID 35933374, 2022).
intestinal polyp (1 paper, 2021). Discrete abnormal tissue masses that protrude into the lumen of the intestine. "MMP-7 null mouse is prone to loss of metaplastic lesions following pancreatic ductal ligation and MMP-7 is important for acinar to ductal metaplasia in PDAC, and inhibition of MMP-7 with a broad spectrum MMP inhibitor reduced the number of intestinal polyps." (PMID 33918254, 2021).
juvenile periodontitis (1 paper, 2022). "With regard to GCF, MMP7 has been reported to be elevated in samples from patients with adult periodontitisrelative to GCF samples collected from patients with localized juvenile periodontitis and controls." (PMID 36518149, 2022).
keloid (1 paper, 2023). An irregularly shaped, elevated mark on the skin caused by deposits of excessive amounts of collagen during wound healing. "It is reasonable to hypothesize that MMP7 may interfere with the construction of extracellular matrix components, resulting in a higher risk of keloid recurrence." (PMID 37685578, 2023). "Five hub genes were linked to keloid recurrence, including CHI3L1, IL1RN, MMP7, TNFAIP3, and TNFAIP6." (PMID 37685578, 2023). "In the present study, the hub genes (CHI3L1, IL1RN, MMP7, TNFAIP3, and TNFAIP6) were mainly involved in the regulation of inflammatory response, IL-17 signalling pathway, and TNF signalling pathway, which is consistent with previous findings in keloids." (PMID 37685578, 2023). "The qRT-PCR experiment was used for detecting the differential expression of five hub genes (CHI3L1, IL1RN, MMP7, TNFAIP3, and TNFAIP6) in recurrent and non-recurrent keloid tissues." (PMID 37685578, 2023).
kidney cancer (1 paper, 2026). Primary or metastatic malignant neoplasm involving the kidney. "MMP7, known for its role in tissue remodeling, was also significantly linked to smoking and influenced kidney cancer development and prognosis." (PMID 40928391, 2026). "Consistent with previous research, we observed elevated levels of HAVCR1, MMP7, and ESM1 in kidney cancer patients." (PMID 40928391, 2026).
lepromatous leprosy (1 paper, 2018). A chronic communicable infection which is a principal or polar form of leprosy. "We analyzed the presence of M4 macrophage markers (CD68, MRP8, MMP7, IL-6, and TNF-α) in 33 leprosy skin lesion samples from 18 patients with tuberculoid leprosy and 15 with lepromatous leprosy by immunohistochemistry." (PMID 30442123, 2018).